TNF (tumor necrosis factor)
Diseases named in the same sentence as TNF in open-access papers (continued):
Sharing a sentence is not in itself a finding about the gene and the disease.
tumor (continued). "M1-type macrophages are critically important in host defense and killing of tumor cells by the production of pro-inflammatory cytokines such as interferon-γ (IFN-γ), TNF-α and IL-18, which have potent microbiome-killing properties and hence are considered as ‘good’ macrophages." (PMID 34646772, 2021). "The two most mentioned cytokines in the tumor microenvironment are TGF-β and TNF-α." (PMID 35069596, 2021). "Moreover, coexpression of Cxcl1 and Ccl2 efficiently attenuated activation of CD8+ and CD4+ T cells in tumour cells ectopically expressing USP12, as evidenced by the changes in the frequencies of TNF-α+IFN-γ+ cells in the populations." (PMID 34381028, 2021). "In particular, we have shown that a cyclic CGisoDGRG peptide (called iso1) coupled to human serum albumin (iso1-HSA) can be used for the functionalization of nanogold bearing TNF or interleukin-12 (IL12), to enable “active” targeted delivery of nanoparticles to the tumor vasculature." (PMID 34124009, 2021). "As MAP4K4 also belongs to the Ste20 family, and like MLK3 is activated downstream of TNFα and feeds into JNK signaling, we hypothesized that MAP4K4 might act upstream of MLK3, thereby enhancing tumor development." (PMID 34511598, 2021). "The HIF-1α signaling pathway appears to be critical to T cell effector function in the setting of hypoxia, as deletion of HIF-1α in T cells lead to decreased production of IFN-γ, granzyme B, and TNFα by CD8 T cells under hypoxic conditions, facilitating tumor growth." (PMID 34868044, 2021). "The secreted factors include interleukin (IL)-1, IL-6, IL-8, tumor necrosis factor-alpha (TNF-α), hepatocyte growth factor (HGF) and vascular endothelial growth factor (VEGF), which in turn promote not only tumor growth but also cancer metastasis in the tumor microenvironment." (PMID 35111685, 2021). "The tumor-infiltrating MAIT-cells produced IFN-γ and TNF, but only little IL-17." (PMID 33885944, 2021). "Researches have shown that miR155 upregulation promotes the differentiation of naive CD4+ T cells into Th1 cells through the regulation of the IFN-γ signal, which is of great significance for T cells to exert anti-tumor function for the secretion of IFN-γ, TNF-α, IL-2 and other cytokines." (PMID 35046962, 2021). "We found that whole-tumor gene expression of T cell marker factors (CD8 and IFN-γ) and chemokines (CXCL9 and CXCL10) were significantly enhanced after ICT treatment, while inflammatory factors (IL6, IL10 and TNF-α) were reduced." (PMID 33460401, 2021). "When incubated with mesothelin-positive tumor cells, Msln-CCR2b-CAR and Msln-CCR4-CAR T cell specifically exerted potent cytotoxicity and produced high levels of proinflammatory cytokines, including IL-2, IFN-γ, and TNF-α." (PMID 33777013, 2021). "Attenuating tumor cell proliferation, Suppressing phosphorylation of downstream signaling cascades ERK and AKT, Triggering secretion of proinflammatory cytokines IFN-γ and TNF-α, and blocking G0/G1 cell cycle." (PMID 33768092, 2021). "Similar to the negative impact of TNFα on anti-tumor immunity, TGFβ supports tumor immune-evasion responses by decreasing the activity of cytotoxic immune cells such as natural killer cells or CD8+ T-cells, while favoring the generation of regulatory T-cells." (PMID 34604096, 2021). "TNF-α is a key driver of checkpoint blockade enterocolitis, but does not appear to have an important role in tumor destruction." (PMID 33407605, 2021). "In tumor microenvironment, gCpG treatment increased Th1 and CTL infiltration, increased M1 macrophages, decreased Tregs and MDSCs populations, and promoted inflammatory milieu with enhanced secretion of IFNγ and TNFα." (PMID 34794428, 2021). "In cases with PBC, serum omentin-1 presented negative associations with tumor biomarkers (CA15-3 and CEA), inflammatory biomarkers (hsCRP, TNF-α, and IL-6), and clinicopathologic features such as stage and the number of infiltrated lymph nodes (p < 0.05)." (PMID 34827610, 2021).
tumor (continued). "Therefore, an MTT assay was performed on TAMs, cultivated with tumor cells in the presence of L-NAME, the iNOS inhibitor, or the neutralizing antibody against TNF-α." (PMID 34205330, 2021). "Strong capability of proliferation, robust potential cytolytic function in eliminating the tumor cells, increased level of TNF-α and IFN-γ production, and no toxicity on healthy HSCs are the reported applications of the CD70-CAR T cell." (PMID 34412685, 2021). "Following short-term restimulation of colonic ILC subsets isolated from tumour-bearing CAC mice with phorbol myristate acetate and ionomycin we observed significant increases in TNF-α (ILC1), IL-5 and IL-13 (ILC2) and IL-17 (ILC3) production in tumour-bearing mice." (PMID 33535624, 2021). "In this way, we observed a higher spleen mass (LW = W) and increased serum content of the pro-inflammatory cytokines IL-6 and TNF-α, which was not significantly different between both tumour-bearing groups (LW = W)." (PMID 34943780, 2021). "Moreover, pro-inflammatory TNF-α or TNF-β, have been previously reported to act as potential endogenous tumor-promoting factors and an important mechanism of cytokines in this action is to induce EMT in different types of tumor cells." (PMID 34276382, 2021). "In chronically stressed mice, mitogen-induced T cell proliferation is reduced, the number of CD4+ T lymphocytes is reduced, and tumor necrosis factor (TNF) and interferon production are reduced, promoting tumor proliferation and progression via inhibition of T cell-mediated immunity." (PMID 34988010, 2021). "The pleiotropic cytokine tumor necrosis factor (TNF) is widely accepted as a central player in the multi-faceted tumor microenvironment, showing a dual role as tumor-promoting or tumor-suppressing, depending on the binding to its receptors TNF 1 (TNFR1) and TNF 2 (TNFR2)." (PMID 34572719, 2021). "Once immune cells were recruited to the tumor lesions, macrophages are extraordinarily abundant and are present in all stages of cancer progression under a gradient of tumor-derived chemo-attractants including CCL-2, tumor necrosis factor (TNF), IL-8, IL-6, VEGF-A, and CSF-1." (PMID 34138315, 2021). "We further found that TNF-α treatment increased not only the phosphorylation of p65 but also the expression of Il-6 in a dose- and time-dependent manner and that treatment with the NF-κB inhibitor BAY-11-7082 reversed the expression of Il-6 in tumour cells." (PMID 33654093, 2021). "In response to interferons, macrophages are polarized and activated into pro-inflammatory classical M1 type that produces cytokines, such as interferon-γ (IFN-γ), tumor necrosis factor-α (TNF-α), IL-23, IL-12, CCL5, CXCL9, CXCL10, and CXCL5 and help destroy tumor cells via activating Th1 cells." (PMID 33925575, 2021). "Ligands including tumor necrosis factor (TNF), Fas ligand (FasL) and TNF related apoptosis inducing ligand (TRAIL) expressed on exosome surface released by dendritic cells can bind to TNF receptors on tumor cells and trigger caspase activation for apoptosis." (PMID 33892745, 2021). "Heightened tumor development upon epidermal-specific TTP ablation was not driven by dysregulated TNF production." (PMID 33497366, 2021). "Moreover, OK-432 induces the production of anti-tumor cytokines, such as interleukin (IL)-2, IL-12, interferon (IFN)-γ, and tumor necrosis factor (TNF)-α from Th1 cells, NK cells, and monocytes/macrophages." (PMID 34209347, 2021). "MAP3K14 (NIK1), BIRC2 (cIAP1), RIPK1, CASP7, CASP8, and TNF play an important role in inhibiting proliferation and invasion of tumor cells via the activation of the non-canonical NF-κB signaling pathway." (PMID 34638912, 2021). "We found that TNF‐α was significantly downregulated by SIRT6 over‐expression in tumour environment, unlike in non‐tumour background." (PMID 34212132, 2021).
tumor (continued). "Besides, the combination treatment also significantly increased the mRNA levels of TRAF3 and GADD45A and the protein levels of TNFα, TRAF3 and GADD45A in the tumor tissues of these mice." (PMID 34025421, 2021). "Moreover, physical interactions between TNBCs and hBMMSCs primed with TNFα or IL-1β, activates Notch1, which leads to CXCL8 production and increased tumor cell migration and invasion." (PMID 33849537, 2021). "TNF-α is a cytokine that can directly kill tumor cells without significant toxicity to normal cells." (PMID 34941034, 2021). "Notably, glucose modification not only greatly increased the tumor-specific killing of CD8+ T cells, but also promoted the infiltration of TNFα- and IFNγ-producing CD8+ T cells in TEM." (PMID 34794428, 2021). "Consistent with previous studies, concomitant analyses of immune activation cytokines indicated that nivolumab treatment also significantly increased the production of IFN-γ, IL-2, and TNF-α, of which IFN-γ has been a key cytokine in IL-10 mediated anti-tumor responses." (PMID 34769278, 2021). "Whether TNF plays a role in resistance to targeting of other RTK nodes and/or in other tumor types is currently unknown." (PMID 33373873, 2021). "TNBC tumor cells were treated with DR5 agonist antibodies and TNF‐α next to each other." (PMID 33587338, 2021). "Clinical trials for PDAC have focused on the targeting of the tumor cells themselves, rather than microenvironment constituents, such as TNF or the factors controlling its production such as NF-κB." (PMID 34572737, 2021). "Moreover, studies have found that STING activation results in pyroptosis by enhancing permeabilization of the lysosome membrane, leading to the necroptosis of tumor cells due to type-I IFN and TNFα production." (PMID 34218252, 2021). "Previous studies indicated that TNF-α is involved in the EMT and tumor progression in cancer cells." (PMID 33730072, 2021). "Studies also showed that systemic TNF treatment did not induce the dramatic anti-tumor effects in patients that had been observed in murine models." (PMID 34553039, 2021). "Despite such high overexpression of TNFα protein in engineered tumor cells, the subpopulation of CSCs responsible for tumor growth initiation remained unaffected, not increased or decreased, and is not directly linked with the loss of tumorigenic potential." (PMID 33957885, 2021). "Upon recognition of the tumor antigen, CAR-T cells release pro-inflammatory cytokines including interferon gamma (IFNγ), interleukin (IL)-1, IL-2 receptor alpha (RA), tumor necrosis factor alpha (TNFα), and IL-6 to induce a cytotoxic response." (PMID 33802788, 2021). "Another study wherein IL-12 was directly injected into mice with lung cancer showed that the IL-12 injection reduced IL-10 and TGF-β levels at the tumor site, which are considered to be signals of the M2 TAM/M phenotype, and increased the expression of IL-6 and TNF-α." (PMID 34394072, 2021). "Upon antigen recognition, tumor-specific CD8+ T cells have an unsurpassed capacity to eliminate tumor cells through the release of proinflammatory cytokines such as interferon (IFN)-γ and tumor necrosis factor (TNF)-α, and cytotoxic molecules including granzyme B and perforin." (PMID 34571883, 2021). "Among these inducers of EMT, which can be also released by the tumor cell, there are growth factors such as the transforming growth factor β (TGFβ) and the hepatocyte growth factor (HGF), as well as cytokines, which include the tumor necrosis factor α (TNFα)." (PMID 34830097, 2021). "Finally, we confirmed the combinational application with tamoxifen, TNFα and short-hairpin NCOR1 showed the enhanced suppressive effect of tumor growth in MCF xenograft mice compared to single tamoxifen treatment." (PMID 34073371, 2021). "M2 TAMs secrete pro-tumor factors (IL-4, IL-6, IL-10, IL-13, EGF, and VEGF), while tumor suppressor M1 TAMs express antitumor factors (IL-12, major histocompatibility complex (MHC) class II, and TNF-α)." (PMID 34341329, 2021).
tumor (continued). "After therapeutic period, Andro could remarkably reduce IL-6, IL-1β, TNF-α, VEGF, MMP-2 level in blood and IL-10, TGF-β, NF-κB level of tumor tissue with significantly statistical implications (p < 0.01)." (PMID 33967748, 2021). "This study suggested that cryosurgery generates the most favourable immune-regulatory response for abscopal tumours and activation of anti-tumour immune cells, and increased secretion of pro-inflammatory cytokines such as IL-1β, IL-2, IL-6, IL-12β, IFN-γ and TNF-α." (PMID 34281259, 2021). "This experiment evaluated the effects of combination therapy and single therapy based on cytokine secretion using ELISA to quantify IFN-γ, TNF-α, IL-2, and IL-10 which is a negative immunoregulatory factor, in tumor tissues." (PMID 33792840, 2021). "Moreover, a variety of tumor immune-related cytokines such as IFN-γ, TNF-α, TGF-β, IL10, and IL4 were notably increased in cells after upregulating the expression of miRNA-542-3p in HepG2 and Huh7 cells and co-cultured with T cells." (PMID 34988028, 2021). "Tumor CD200 expression was correlated with significantly decreased tumor infiltration from CD4-positive and CD8-positive T cells and decreased production of IFNγ and TNFα." (PMID 33804482, 2021). "Tumor necrosis factor-α (TNF-α) is one of the primary proinflammatory cytokines produced by CD4+ TH1 cells and binds to two receptors, TNFR1 and TNFR2, that promote cell death and destruction of tumor vasculature." (PMID 34012451, 2021). "Noteworthy, the combined therapy with LCL-SIM and LCL-DMXAA strongly reduced (by 50–81%) the intratumor production of bFGF, IL-1 α/β, IL-6, TNFα, leptin and of eotaxin, which allow cancer cells to escape VEGF-targeted therapies, promoting tumor growth and metastasis." (PMID 34764332, 2021). "Similarly, for lymphocytes, tumor growth can be regulated by secreting cytokines, like IFN-γ and TNF-α." (PMID 34616680, 2021). "These cells are capable of stimulating an antitumor immune response through presenting antigens to adaptive immune cells, producing proinflammatory cytokines such as IL-1β, IL-6, IL-12 and TNFα in addition to chemotactic factors such as IL-8 and MCP-1, as well as by phagocytosing tumour cells." (PMID 34944870, 2021). "In addition, higher IL2, IFN-γ, and TNF families (e.g. CD40) represents a favorable cellular immunity and anti-tumor ability of C3." (PMID 33637086, 2021). "TNF-α leads to reduced OPG production, thereby stimulating osteoclastogenesis and tumor growth." (PMID 34064859, 2021). "The blockade of TNFα and IL1β with adalimumab and anti-IL1β antibody respectively, as well as the application of focal adhesion kinase (FAK) inhibitor, effectively ameliorated endothelial activation induced by CAR-T, tumor cells, and myeloid cells." (PMID 34093519, 2021). "In addition, fullerenols decreases intra-tumor MVD in vivo, probably by down-regulating TNF-α, VEGF and PDGF expression." (PMID 34071369, 2021). "A similar conclusion was obtained in a study of ginseng berry polysaccharide portion (GBPP), which stimulated macrophages to secrete anti-tumorigenic cytokines (e.g., IL-6, IL-12, TNF-α) while also promoting NK cells to release IFN-γ and granzyme B that inhibited tumor cells activities." (PMID 35002732, 2021). "Unfortunately, some tumor types showed no benefit from the combination regime of the gold standard with TNFα blocking agents." (PMID 33540543, 2021). "In this model, the irAEs appeared because of an infiltration of effector T cells in the tissues, however, TNFα blockade decreased the irAEs severity without impacting tumor growth rate." (PMID 33571254, 2021). "5-FU alone can only promote the expression of IFN-γ and TNF-α in tumor-bearing mice but demonstrated no evident effect on IL-2." (PMID 34803677, 2021). "To determine whether the functions of immune cells such as T cells were impacted by the lack of the CD200-CD200R interaction, we quantified IFN-γ and TNF-α levels in CD4+ and CD8+ tumor infiltrating lymphocytes (TIL)." (PMID 34692697, 2021).
tumor (continued). "We found that the tumor load in tnf−/− mice was comparable to wildtype mice and injection of anti-TNF into the mice did not prevent tumor cells from extravasating and forming tumor nodules in the lung." (PMID 33546280, 2021). "The requisite presence of TNFα, which is presumably more abundant in tumor vs. non-tumor endothelium perhaps explains the absence of RRx-001-related side effects in treated vasculopathic patients with cancer." (PMID 33946824, 2021). "Consistently, injecting the STING agonist, cGAMP, into the tumor exhibited effective anti-tumor responses by recruiting and activating M1 phenotype TAMs in a STING-dependent manner via producing TNF-α, type I IFN, and T-cell-attracting chemokines to mediate various immune responses." (PMID 34956229, 2021). "We prepared bi- or trifunctional nanoparticles bearing tumor necrosis factor-α (TNF) and/or interleukin-12 (IL12) plus a peptide containing isoDGR, and we tested their anti-cancer effects, alone or in combination with doxorubicin, in tumor-bearing mice." (PMID 33952242, 2021). "As tumor spheroids are formed primarily by cancer stem cells (CSCs) and require the formation of cell-to-cell contacts, we next determined the stemness of TNBC cells that have been persistently stimulated by TNFα + IL-1β." (PMID 34072893, 2021). "In both tumor types pFUS increased IL1α, IL1ß, IL2, IL6, IL12p40, IL15, IL17, TNFα, and VCAM." (PMID 33801627, 2021). "Primary tumor prepares distant niches by releasing tumor-derived secreted factors, including pro-angiogenic factors (e.g., Vascular Endothelial Growth Factor (VEGF)) and pro-inflammatory factors (e.g., Tumor Necrosis Factor α (TNFα), Transforming Growth Factor β (TGF-β), Interleukins (ILs))." (PMID 33800796, 2021). "In contrast, tumor-related factors such as TNFα and G-CSF had no influence on NDN plasticity in both AB12 and 4T1-derived neutrophils." (PMID 34680231, 2021). "Altogether, ILC cells including NK cells could contribute to the increased level of TNF-alpha, GM-CSF, IFN-gamma, IL-4, IL-5, IL-13, IL-17, and IL-22, modulating TME and contributing to tumor progression or antitumor activities." (PMID 35008550, 2021). "Mechanistically, the lack of Treg expansion observed in the tumor microenvironment is mediated by CD8+ T‐cell‐associated cytokines, including IFNγ and TNFα, which are released in response to cognate tumor antigen recognition in the tumor tissue." (PMID 33152115, 2021). "CircIGF2BP3 depletion alleviated tumor cell-mediated immune suppression, as determined by the expression of perforin, granzyme B (GzmB) and secreted IFN-γ and TNF-α from cocultured PBMCs, whereas circIGF2BP3 overexpression compromised the expression or secretion of these immune effectors." (PMID 34416901, 2021). "Unpolarized or M1 polarized macrophages could be loaded with proinflammatory and M1 polarizing stimuli, such as TNF-α, IFN-γ, or IL-6 to support a proinflammatory environment at the tumor site." (PMID 37849947, 2021). "Furthermore, RHWPs also markedly increased the levels of TNF-α, IFN-γ, and IL-2 in the sera of tumor-bearing mice, and activated immune cells such as lymphocytes, NK cells, and macrophages, thereby inducing tumor cell apoptosis." (PMID 33921554, 2021). "In tumors, for example, interleukin 1 (IL-1), IL-8, and tumor necrosis factor (TNF) are able to recruit immune cells, allowing for the removal of deleterious senescent and neighboring cells in a way that is consistent with the anti-tumor role of senescence." (PMID 35008679, 2021). "However, previous studies have suggested that lymphocytes interplay in controlling tumor growth via secreting cytokines such as interferon gamma (IFN-γ) and tumor necrosis factor alpha (TNF-α)." (PMID 33989285, 2021). "Addition of the TLR4 inhibitor peptide but not the CP7 control peptide inhibited LPS-induced TNF-α production in all BIA-ALCL tumor cells." (PMID 34771464, 2021).